LRP8-DT (LRP8 divergent transcript)
Synonyms: formerly LINC01771
Gene: Long non-coding RNA gene on chromosome 1 (53,328,220 to 53,363,914, forward strand). Ensembl gene ENSG00000225675.
Diseases named in the same sentence as LRP8-DT in open-access papers:
LRP8-DT is named in the same sentence as 1 disease in open-access papers, as found by Europe PMC text mining. Sharing a sentence is not in itself a finding about the gene and the disease.
LRP8-DT shares sentences with these, for which no sentence is quoted: asthma (1 paper).